CD1C (CD1c molecule)
Diseases named in the same sentence as CD1C in open-access papers (continued):
Sharing a sentence is not in itself a finding about the gene and the disease.
systemic lupus erythematosus (15 papers, 2014 to 2025). An autoimmune multi-organ disease typically associated with vasculopathy and autoantibody production. "Thus we considered that the defect of FLT3L was at least partly contributed to the deficiency of CD1c+DCs in lupus patients." (PMID 31175312, 2019). "After transplanting of umbilical cord-MSCs, the significantly upregulated levels of FLT3L promoted the proliferation and inhibited the apoptosis of tolerogenic CD1c+ DCs, thereby improving the condition of lupus." (PMID 34659214, 2021). "In this study, we found that the level of FLT3L significantly decreased in peripheral blood in patients with SLE, and human recombinant FLT3L stimulation significantly increased the proportion of CD1c+DCs in lupus PBMCs in vitro." (PMID 31175312, 2019). "We have revealed a previously unrecognized IFNγ-FLT3L-FLT3 axis in allogeneic UC-MSCs-mediated increase in CD1c+DCs in lupus patients." (PMID 31175312, 2019). "Our previous study revealed that molecular alterations in mDCs (CD1c+) and pDCs from lupus patients significantly influence the hyperactivated B cells, mainly through secretory and expression activity [unpublished data]." (PMID 31507612, 2019). "Conversely, reduction of FLT3L with small interfering RNA in MSCs abolishes the up-regulation of tolerogenic CD1c+DCs in lupus patients treated with MSCs." (PMID 31175312, 2019). "In support of this conclusion, we demonstrated that UC-MSCs transplantation remarkably up-regulated the level of serum FLT3L along with an increase of CD1c+DCs in lupus patients." (PMID 31175312, 2019). "The number of CD1c+DCs was negatively correlated with systemic lupus erythematosus disease activity index (SLEDAI) score." (PMID 31175312, 2019). "Collectively, our data demonstrated that in lupus microenvironment, UC-MSCs not only increased the number of CD1c+DCs, but also drived CD1c+DCs towards a more tolerogenic phenotype." (PMID 31175312, 2019). "We also found that prednisone-treated lupus patients had increased Mer expression on their CD1c+ myeloid DCs." (PMID 24650765, 2014). "We observed an increase in expression of Mer on CD1c+ mDCs and also in plasmacytoid DCs in lupus blood." (PMID 24650765, 2014). "Among DCs, a significant increase in the levels of Mer expression was found in both pDCs and in CD1c+ myeloid DCs from lupus patients compared with healthy control subjects." (PMID 24650765, 2014). "Thus, we uncover a previous unrecognized IFN-γ/FLT3L-FLT3/CD1c+DCs axis that mediates the therapeutic benefit of allogeneic UC-MSCs in lupus." (PMID 31175312, 2019). "In addition, we found the UC-MSCs induced CD1c+DCs in the lupus patients exerted tolerogenic properties by decreasing expression of CD80, CD83, CD86 and HLA-DR, decreasing production of TNFα and keeping production of IL-10." (PMID 31175312, 2019). "A study reported that intravenous infusion of umbilical cord MSCs in patients with Systemic lupus erythematosus (SLE), resulting in the increased frequency of CD1c+ dendritic cells." (PMID 37237538, 2023). "In systemic lupus erythematosus (SLE), DN T cells reactive to CD1c can produce IL-4 and IFN-γ, and may support IgG production by CD1c+ B cells." (PMID 40709176, 2025). "Here the authors show that MSCs expand CD1c+ dendritic cells in cell culture by producing FLT3L, and that in lupus patients, circulating CD1c+ dendritic cells and FLT3L are increased following MSCs therapy." (PMID 31175312, 2019). "Allogeneic UC-MSCs promote the proliferation and inhibit the apoptosis of tolerogenic CD1c+DCs by up-regulating FLT3L in SLE patients, which could be enhanced by the high level of IFN-γ in lupus environment." (PMID 31175312, 2019). "A circulating CD1c+CD14+CD163+ cDC2 subset, related to the DC3s, was found to expand correlatively with disease activity in patients with systemic lupus erythematosus (SLE)." (PMID 34566965, 2021).
psoriasis (14 papers, 2007 to 2025). An autoimmune condition characterized by red, well-delineated plaques with silvery scales that are usually on the extensor surfaces and scalp. "Type 1 mDCs are known as resident dendritic cells, and are antigen presenting cells (APCs) that present to T lymphocytes, they are BDCA-1-positive (CD1c+), and numbers are normal in psoriasis." (PMID 38785955, 2024). "In inflammatory skin conditions including psoriasis, in addition to LC, CD1c+ DC, and CD141+ DC that are already present during the steady state, pDC and iDC migrate into the skin." (PMID 35837394, 2022). "These iDC in psoriasis are identified as CD11c+CD1c− DC, distinguishing them from resident cDC, and are assumed to be derived from monocytes." (PMID 35837394, 2022). "CD1c+ DCs are cDCs found in healthy skin, in psoriasis and at increased numbers in the dermis in AD." (PMID 29977237, 2018). "The numbers of CD11c+ cells in psoriasis are many fold greater than CD1c+ cells, as CD11c identifies both the resident myeloid DCs and a population of “inflammatory” myeloid DCs." (PMID 22348003, 2012). "In contrast to resident CD1c+ DCs, CD11c+ cells are increased in psoriasis, reduced with treatment, and increased during relapse." (PMID 22348003, 2012). "This is very different from psoriasis where CD1c+ cells arenot increased, but inflammatory CD11c+ CD1c− DCs are seen to expand in adramatic manner." (PMID 21541348, 2011). "IL-23, which is part of the IL-12 family, is produced by both resident [blood dendritic cell antigen (BDCA-1)/CD1c+] and inflammatory myeloid DCs (CD11c+ BDCA-1/CD1c–), as well as macrophages (CD163+) in psoriasis." (PMID 38793117, 2024). "Type 2 mDCs are BDCA-1-negative (CD1c−), with numbers greatly increased in psoriasis lesions, and normalising after treatment with biologics." (PMID 38785955, 2024). "The number of CD1c+ DC was lower in non-lesional and lesional skin of psoriasis patients than in normal skin, whereas the number of CD141+ DC was higher." (PMID 35837394, 2022). "Consistent with previous anti-psoriasis treatments, BDCA-1/CD1c did not change with disease state, efalizumab treatment or relapse." (PMID 22348003, 2012).
leukemia (11 papers, 2013 to 2025). A malignant (clonal) hematologic disorder, involving hematopoietic stem cells and characterized by the presence of primitive or atypical myeloid or lymphoid cells in the bone marrow and the blood. "Furthermore, co-targeting CD1c with other already available leukemia-restricted antigens could also minimize the antigen loss leading to immune evasion." (PMID 34381053, 2021). "Further understanding of the lipidome of malignant leukemic cells and identification of tumour specific lipid antigens will allow to develop lipid-specific TCR-based T cell engagers a new class of off-the shelf immunotherapeutic for CD1c positive leukemias." (PMID 40777002, 2025). "The strongest association was for SRP14 with leukaemia [1.22 (1.16–1.28)] followed by KRT18 for liver cancer [1.29 (1.18–1.42)], CD1C for NHL [1.11 (1.06–1.16)] and TNR for lung cancer [0.92 (0.89–0.95)." (PMID 38750076, 2024). "Here the authors engineered T cells with a TCR specific for a CD1c restricted lipid leukaemia antigen and show that they can protect against disease progression in mouse leukaemia xenograft models." (PMID 34381053, 2021). "Taken together, these data identified DN4.99 as the lead TCR for further development due to its high level of expression, strongest endogenous TCR repression, strongest reactivity against CD1c-expressing leukemia cells and mLPA specificity." (PMID 34381053, 2021). "In conclusion, our results support the use of mLPA-specific CD1c-restricted T cell as an attractive option for adoptive immunotherapy of leukemia across MHC barriers." (PMID 34381053, 2021). "An example is provided by CD1c-restricted T cells recognizing methyl lysophosphatidic acids (mLPA), a newly defined lipid species accumulating in leukemia cells." (PMID 29963057, 2018). "mLPA-specific T cells recognized and killed CD1c+ leukemia targets and limited leukemia cell spread in a mouse model." (PMID 29963057, 2018). "Autoreactive CD1c-restricted T cells were found to recognize methyl-lysophosphotidic acid, a novel class of self-lipids, which accumulate in leukemia cells." (PMID 26175733, 2015). "While these autoreactive CD1c-restricted T cells poorly recognize non-tumor CD1c-expressing cells, they killed CD1c+ acute leukemia cells and protected immunodeficient mice against CD1c+ human leukemia cells." (PMID 26175733, 2015). "Recently, we have identified the novel self lipid methyl-lysophosphatidic acids (mLPA), not described before, which accumulates in myeloid and lymphoid leukemia cells and induces a CD1c-restricted response directed against these human leukemias." (PMID 24904574, 2014). "For example, the combination of GM-CSF, IL-4, and TNFα induced the expression of MHC II, CD40, CD86, CD1a, CD1b, and CD1c by neutrophil-committed precursors isolated from leukemia patients receiving G-CSF treatments." (PMID 24278484, 2013). "These proof-of-concept findings demonstrate that CD1c targeting TCR bispecific engagers might be good candidates for the development of non-MHC restricted, universal therapeutics for the treatment of CD1c+ leukemias." (PMID 40777002, 2025). "CD1c+ restricted T cells exhibit potent anti-leukemia activity in mouse models, indicating that this lipid antigen may represent a new target for immunotherapy of hematological malignancies." (PMID 38099311, 2023). "Here, we show that human T cells engineered to express an mLPA-specific TCR, target diverse CD1c-expressing leukemia blasts in vitro and significantly delay the progression of three models of leukemia xenograft in NSG mice, an effect that is boosted by mLPA-cellular immunization." (PMID 34381053, 2021). "Leukemia blasts express CD1c antigen-presenting molecules, which are identical in all individuals and expressed only by mature leukocytes, and are recognized by T cell clones specific for the CD1c-restricted leukemia-associated methyl-lysophosphatidic acid (mLPA) lipid antigen." (PMID 34381053, 2021).
leukemia (continued). "Importantly, the same CD1c-restricted T cells strongly recognized and killed CD1c+ leukemia cells, which already have high mLPA quantities." (PMID 29963057, 2018). "The unique availability of a defined leukemia-enriched self-lipid antigen also provides us with the opportunity to boost the engineered T cell response with mLPA-containing vaccines, in turn stimulating and enhancing the efficacy of the CD1c-targeting ACT strategy." (PMID 34381053, 2021). "mLPA-specific T cell clones were shown to efficiently kill in vitro and in vivo primary leukemia cells in a CD1c-restricted manner, but not normal B cells and primary DC, that despite being CD1c positive do not express the antigen at significant level." (PMID 26284072, 2015). "mLPA-specific T-cells efficiently kill CD1c+ acute leukemia cells, and protect immunodeficient mice against CD1c+ human leukemia cells and poorly recognize non-transformed CD1c-expressing cells." (PMID 24904574, 2014). "Indeed, it has been demonstrated that CD1c-restricted T cells can target leukemia cell lines in a CD1c-dependent manner while sparing CD34+ stem cells, and CD1c has been shown to be expressed in AML, T-ALL, B-ALL blasts and non-Hodgkin lymphomas in 50-75% of patients." (PMID 40777002, 2025). "Our strategy allows the generation of “universal” effector T cells for a donor-unrestricted application of ACT to any patient bearing CD1c-expressing leukemia: moreover, in an allogeneic HSCT setting, the risk of GvHD should be minimized upon ACT given the absence of CD1c on parenchymatous tissues." (PMID 34381053, 2021).
breast carcinoma (10 papers, 2020 to 2025). "CD1c+CD14+ DC3 frequency is positively associated with the presence of tissue-resident memory CD8+ T cells in Luminal A-type breast cancer." (PMID 40584260, 2025). "For instance, in breast cancer, the transcriptional profiles of infiltrating CD1c+CD14+ DCs and other DC populations were extensively studied, revealing their subset-specific adaptation to the TMEs of different breast cancer types." (PMID 40584260, 2025). "Gene co-expression analyses were performed and the retrieved immunologically related genes were used to further investigate CD1C-related immune functions in breast cancer." (PMID 36755259, 2023). "The difference between CD1C levels and lymph node metastasis of breast cancer was also statistically significant." (PMID 36755259, 2023). "CD1C levels were positively correlated with CD8+T, CD4+T, and NK cells, explaining the protective roles of CD1C in breast cancer." (PMID 36755259, 2023). "Elevated CD1C levels correlated with good prognostic outcomes for breast cancer patients, implying that CD1C is involved in inhibition of tumor progression." (PMID 36755259, 2023). "In the Pre group, cDC (CD1C) was the predominant cell type present in iCCA and breast cancer." (PMID 39034339, 2024). "In summary, CD1C is a prognostic biomarker for breast cancer and a potential treatment target." (PMID 36755259, 2023). "CD1C is expected to become a prognostic marker and a new treatment target for breast cancer." (PMID 36755259, 2023). "The general trend is that the expression of CD1C is higher in early breast cancer." (PMID 36755259, 2023). "We conclude that CD11c+FcεRI +CD14+CD1c+ iDCs infiltrating breast cancer align with DC3s." (PMID 32610077, 2020). "In breast cancer (BRCA), the expression of CD1c correlated with BRCA prognosis and clinical features." (PMID 38099311, 2023). "Due to the lack of data on breast cancer patients, data of kidney cancer patients from the database were used to analyze the impact of CD1C on immunotherapy." (PMID 36755259, 2023). "Interestingly, expression of some immune cell genes and DVL-1 uniquely correlated with luminal breast cancer, such as CD19, CD79A, CD8B, CCR7, CD1C, and STAT5B." (PMID 34659647, 2021). "Finally, although the effect of CD1C on immunotherapy in patients with renal cell carcinoma was confirmed by the TIDE database, the impact of CD1C on immunotherapy is not clear in breast cancer patients." (PMID 36755259, 2023).
HIV-1 infection (9 papers, 2013 to 2025). The type species of lentivirus and the etiologic agent of acquired immunodeficiency syndrome (AIDS). "While cDC1 (CD141+) are resistant to productive HIV-1 infection, they can cross-present viral antigens derived from cDC2 (CD1c+) that are susceptible to HIV-1." (PMID 29250073, 2017). "Thirdly, downregulation of CD1c molecules by HIV-1 infection weakened the ability of CD1c-restricted T cells to respond to and secrete interferon-γ." (PMID 26286082, 2015). "Our findings are the first to describe endogenous lipid presentation and the functions of CD1c-restricted T cells during HIV-1 infection." (PMID 23347583, 2013). "If CD1c + mDC stimulation is suppressed, HIV-1 infection will progress to AIDS rapidly." (PMID 26286082, 2015). "Taken together with our finding that the concurrent cholesterol production induced by HIV-1 virus decreased the extent of CD1c modulation, these data may be useful for exploiting the maintained CD1c levels expressed during HIV-1 infection." (PMID 23347583, 2013). "HIV-1 infection induces the production of cholesterol, which may be presented by CD1c/CD1d molecules to initiate an immune response." (PMID 23347583, 2013). "Thus, the decrease in CD1c expression during HIV-1 infection appears to affect the ability of CD1c-restricted T cells to recognize infected cells." (PMID 23347583, 2013). "Thus, our data showing CD1c downregulation during HIV-1 infection may indicate one of the HIV-1 immune evasion mechanisms." (PMID 23347583, 2013). "It is also possible that hBD-2PTD and/or hBD-3PTD may inhibit HIV-1 infection in CD4+ T lymphocytes, CD68+ macrophages, and CD1c+ DC in the tonsil tissue." (PMID 34696473, 2021). "While the modest downregulation of CD1c by HIV-1 infection decreased the ability of CD1c-restricted T cells to respond and secrete interferon-γ, the cholesterol upregulation in the same cells by HIV-1 infection appears to limit the downregulation of CD1c." (PMID 23347583, 2013). "We found that HIV-1 infection induced the downregulation of CD1c and CD1d expression through a Vpu-dependent, Nef-independent mechanism, and the concomitant HIV-1-induced production of host cholesterol decreased the extent of CD1c and CD1d modulation." (PMID 23347583, 2013). "We found Tat-induced methylation variations in genes such as TNF, CD1C, and CD1D, belonging to pathways involved in the binding, processing, and presentation of lipid antigens, immune response, and inflammatory pathways, which are processes well-documented during HIV-1 infection." (PMID 40103825, 2025). "Based on our findings that an increase in cholesterol production resulted in increased stimulation of CD1c-restricted T cells and studies by other groups showing that HIV induces cholesterol production, we next assessed the level of CD1c expression during HIV-1 infection." (PMID 23347583, 2013). "mDC (CD1c+), SLAN+ DC and CD14+ monocytes were most efficient in stimulating proliferation of CD4+ T-cells during syngeneic culture and in generating post-integration latent infection in non-proliferating CD4+ T-cells following HIV-1 infection of APC-T cell co-cultures." (PMID 26362311, 2015).
viral infection (8 papers, 2015 to 2025). "P. timonensis bacteria enhanced HIV‐1 transmission by CD1c+ DCs, but not by moDCs, and the enhanced transmission was independent of viral infection." (PMID 40071689, 2025). "Myeloid/classical DCs (mDCs) express typical myeloid antigens (CD11c, CD13, CD33, CD11b) with the majority of them expressing CD1c/BDCA1, while plasmacytoid DCs (pDCs) express CD123, CD303/BDCA2, CD304/BDCA4, and produces IFNα after activation with CpG or viral infection." (PMID 32676075, 2020). "Increased CCR7 expression on blood CD1c+ MDCs during acute HFRS could indicate that these cells have migrated to the lymph nodes, in response to either direct viral infection, as we could show in vitro, or to pro-inflammatory cytokines in serum of patients." (PMID 28640917, 2017). "Accordingly, others reported that CD1c+ and CD16+ mDCs were characterized by different allostimulatory functions and unique responses to Toll-like receptor ligands suggesting that they may potentially have different responses to bacteria or viral infection." (PMID 25915601, 2015).